WNT5A (Wnt family member 5A)
Diseases named in the same sentence as WNT5A in open-access papers (continued):
Sharing a sentence is not in itself a finding about the gene and the disease.
colon adenocarcinoma (2 papers, 2015 to 2024). "We found that, among 19 Wnt ligands, WNT2 and WNT5A are highly upregulated in colon mucinous adenocarcinoma, rectal adenocarcinoma, colon adenocarcinoma, and cecum adenocarcinoma." (PMID 26484565, 2015).
colorectal tumor (2 papers, 2011 to 2019). "Wnt5a is a critical regulator of non-canonical Wnt activity and promoter hypermethylation of this gene has emerging prognostic roles in CRC; however the frequency and prognostic significance of this epigenetic event have not been explored in the context of colorectal tumour subtype." (PMID 21587258, 2011).
depression (2 papers, 2022 to 2024). "Similarly, IGF1/IGF1R signaling declined during pregnancy, which is notable given that IGF1 deficiency in the hippocampus is linked to depression Wnt5a signaling in endothelial cells also declined during pregnancy compared with virgin." (PMID 36239981, 2022). "In contrast, treadmill exercise combined with a high-fat diet effectively ameliorates depression-like behavioral phenotypes by improving hippocampal synaptic plasticity, which depends on Wnt5a/CamkII/mTOR signaling pathway-mediated autophagy activation." (PMID 39389946, 2024). "In summary, the Wnt5a/CamkII/mTOR signaling pathway identified in this study provides new insights into how exercise alleviates HFD-induced depression-like behaviors." (PMID 39389946, 2024). "Therefore, this work highlights the critical role of Wnt5a, which is necessary for exercise to improve high-fat diet-induced depression." (PMID 39389946, 2024). "Based on these findings, we hypothesize that regular exercise activates hippocampal neuronal autophagy to enhance synaptic plasticity through the regulation of the Wnt5a/CamkII pathway, thereby preventing or alleviating depression-like behavior induced by a high-fat diet." (PMID 39389946, 2024).
embryonal carcinoma (2 papers, 2010 to 2012). A non-seminomatous malignant germ cell tumor characterized by the presence of large germ cells with abundant cytoplasm resembling epithelial cells, geographic necrosis, high mitotic activity, and pseudoglandular and pseudopapillary structures formation. "Totipotent mouse embryonal carcinoma F9 cells transfected to express rat Frizzled-2 (Fz2) provided an optimal system for the biochemical analysis of Wnt5a/Fz2 signaling." (PMID 21092292, 2010). "To confirm that Wnt5a is expressed in cardiac progenitors, we carried out qRT-PCR on the P19CL6 mouse embryonal carcinoma cell line that is able to differentiate into cardiomyocyte progenitors upon 5-azacytidine and/or DMSO treatment." (PMID 22438823, 2012).
hyperuricemia (2 papers, 2022). An abnormally high level of uric acid. "It has been demonstrated that Wnt5a plays an emerging role in hyperuricemia-induced kidney tubular injury." (PMID 35239776, 2022). "Experiments in vivo and in vitro have shown that hyperuricemia may induce renal tubular injury mediated by epithelial-mesenchymal transition (EMT) through the activation of Wnt5a or the TLR4/NF-κB signaling pathway." (PMID 35156903, 2022).
hypopharyngeal cancer (2 papers, 2020 to 2022). Carcinoma, predominantly squamous cell, arising from the epithelial cells of the hypopharynx. "We demonstrate that the administration of BAY 11-7082, either before or after acidic bile, eliminates NF-κB activation, prevents overexpression of Bcl2, Rela, Stat3, Egfr, Tnf, Wnt5a, and deregulations of miR-192, miR-504, linked to bile reflux-related hypopharyngeal cancer." (PMID 32934775, 2020). "Next, we will explore whether WNT5A has the same effect of radiotherapy resistance in other HNSCC tumors, such as hypopharyngeal cancer." (PMID 35517407, 2022).
insulinoma (2 papers, 2021 to 2024). "Our previous studies demonstrated that ISCs regulate insulin secretion and apoptosis in the MIN6 insulinoma cell line via the secretion of Wnt5a and activation of the FoxO1‐PDX1‐GLUT2‐insulin signaling cascades." (PMID 38185936, 2024).
intestinal tumor (2 papers, 2016 to 2023). "The aberrant expression of WNT5A in intestinal tumor microenvironments is well documented." (PMID 37722040, 2023). "However, increased expression of WNT-5A is not sufficient to augment malignancy or metastasis in APC-driven intestinal tumor model suggesting that additional, not yet understood, mechanisms govern WNT-5A activity at different stages of cancer pathogenesis." (PMID 26514730, 2016).
ischemic stroke (2 papers, 2022 to 2023). A stroke disorder caused by obstruction of blood flow to the brain, due to thrombotic (local blood clot formation) or embolic (due to a blood clot or other material traveling from another site) event. "As a result, Wnt5a expression is reduced, and so is its inflammatory signaling in RPE cells and neurons in ischemic stroke." (PMID 35622188, 2023). "Wnt5a triggers inflammatory responses and damage via NFkB/p65 in retinal pigment epithelial (RPE) cells undergoing uncompensated oxidative stress (UOS) and in experimental ischemic stroke." (PMID 35622188, 2023).
kidney (2 papers, 2016 to 2023). "In conclusion, our results verify the reno-protective potential of AEA against HgCl2-induced kidney injury by its anti-inflammatory, antioxidant, and anti-apoptotic capacities by modulating WNT-5A/BCL-2, IP3/NFATC1, HMGB-1/RAGE/NF-κB, caspase-1/IL-18, and caspase-3/BCL-2 cues." (PMID 37488162, 2023). "We sequenced the coding region and the intron-exon boundaries of human WNT5A (NM_003392) in a cohort of 129 CAKUT and Alport syndrome patients with either a duplex collecting system, renal agenesis, horseshoe kidney or Alport syndrome with unknown cause." (PMID 26794322, 2016).
Kidney Cyst (2 papers, 2020 to 2023). Abnormal fluid filled sac within the kidney, either acquired or congenital. "Increased Wnt5a expression in zebrafish led to kidney cyst formation in all nephron structures, signifying Wnt5a’s importance for correct kidney morphogenesis." (PMID 32365994, 2020). "Wnt5a has a role in PCP regulation in mice, and disruption in the PCP pathway has been shown to result in kidney cyst formation." (PMID 37238991, 2023). "Wnt5a/b functions in planar cell polarity regulation in mice and disturbance in the PCP pathway has resulted in kidney cyst formation." (PMID 37238991, 2023).
lentivirus infection (2 papers, 2021). Virus diseases caused by the Lentivirus genus. "To further validate the notion that GC exosomes educated BM-MSCs using Wnt5a signaling, we overexpressed Wnt5a in AGS cells using lentivirus infection (pLV-Wnt5a) and obtained Wnt5a-enriched AGS exosomes." (PMID 33654199, 2021).
liver disease (2 papers, 2009 to 2023). "Previous data additionally suggest regulation of the Wnt5a/SFRP5 system in liver disease including non-alcoholic fatty liver disease (NAFLD)." (PMID 36830849, 2023). "Thus, Wnt5a upregulation observed in clinical samples might be related to HBV at least in HBV-related liver diseases." (PMID 19849855, 2009).
malignant glioma (2 papers, 2017 to 2018). A grade III or grade IV glioma arising from the central nervous system. "To fully explore the association of Wnt5a expression with survival in all malignant gliomas, we conducted univariate and multivariate Cox regression analysis to assess the prognostic independence of Wnt5a expression among other factors." (PMID 29531296, 2018). "Increasing Wnt5a was independently correlated with a worse outcome in malignant glioma patients in the GSE16011 data set." (PMID 29531296, 2018). "Increasing Wnt5a expression was correlated with a worse outcome in malignant glioma patients in all included data sets." (PMID 29531296, 2018). "Immunohistochemical staining of the adjacent normal brain tissues of malignant glioma revealed that Wnt5a levels were consistently expressed in the neurons, this result was consistent with previous study; however, the Wnt5a levels were decreased with the increase of age." (PMID 29033786, 2017).
metabolic syndrome (2 papers, 2016 to 2022). A cluster of metabolic risk factors for CARDIOVASCULAR DISEASES and TYPE 2 DIABETES MELLITUS. "Therefore, we found decreased expression of WNT5A in VAT (p = 0.034) and of PPARγ in SAT (p = 0.035) samples in patients presenting metabolic syndrome." (PMID 36077270, 2022). "Hence, we found decreased expression of WNT5A in SAT in diabetic patients and reduced expression of WNT5A in VAT in metabolic syndrome patients." (PMID 36077270, 2022).
Mycobacterium infection (2 papers, 2016 to 2019). Infections with bacteria of the genus Mycobacterium. "Mycobacterium infection or the presence of LPS induces WNT-5A expression in human antigen presenting cells and T cells in a TLR-NFκB-dependent manner where it mediates expression of IL-12 and IFNγ contributing to the antimicrobial defense." (PMID 26514730, 2016). "WNT-5A is proposed to regulate cell fate via FZD6 in hair follicles, whereas it plays critical role in tuberculosis immunology via FZD5 regulating immune responses by antigen presenting cells and activated T cells in response to mycobacterium infection." (PMID 26514730, 2016).
neuropathy (2 papers, 2019 to 2025). A disorder affecting the nervous system that manifests with pain, tingling, numbness, and/or muscle weakness. "The shared involvement of the Wnt5a signaling pathway in both HIV and ART-induced neuropathy highlights a key target for future therapeutic interventions." (PMID 41480619, 2025).
non-melanoma skin carcinoma (2 papers, 2012 to 2015). "In conclusion, we here show that Wnt5a is overexpressed in non-melanoma skin cancer, localises to the invasive tumor edge, and directs gradient – dependent motility of keratinocytes in vitro." (PMID 22384081, 2012). "Collectively, our data strongly suggest that Wnt5a signalling contributes to tissue invasion by non-melanoma skin cancer." (PMID 22384081, 2012). "Additionally, Wnt5a signaling was found to contribute to tissue invasion by non-melanoma skin cancer, including both SCC and BCC." (PMID 26394929, 2015). "Expression of Wnt5a, Fzd3, and Fzd5 in non-melanoma skin cancer." (PMID 22384081, 2012).
Pain (2 papers, 2022 to 2025). An unpleasant sensory and emotional experience associated with actual or potential tissue damage, or described in terms of such damage. "In particular, inhibition of Wnt5a ameliorates the exacerbation of HIV-related neuropathic pain, induced by continuous morphine administration." (PMID 36231105, 2022). "Notably, treatment of HIV-PAIN with opioids can temporally alleviate severe pain, but repeated morphine is another trigger in upregulating the Wnt5a pathway and worsens the existing allodynia and promoted astrogliosis in the SDH in mice." (PMID 41480619, 2025).
pancreatic ductal adenocarcinoma (2 papers, 2021 to 2023). An infiltrating adenocarcinoma that arises from the epithelial cells of the pancreas. "Early gene profiling studies indicate that Wnt5a, a marker of the non-canonical wnt molecule is up-regulated in pancreatic ductal adenocarcinoma cells." (PMID 33661942, 2021).
peripheral arterial disease (2 papers, 2017 to 2021). A disorder of the arteries supplying the upper and lower extremity and the visceral organs. "Previous work has established Wnt5a as a pro-inflammatory molecule in a number of settings including vascular dysfunction, peripheral arterial disease, and cardiometabolic disease." (PMID 28724439, 2017). "It has been shown that Wnt5a contributes to increased cardiac dysfunction following ischemia/reperfusion injury and to impaired revascularization in a model of peripheral arterial disease." (PMID 28724439, 2017). "In the adipocytes of patients with the peripheral arterial disease (PAD), the plasma concentrations of WNT5A are significantly increased but those of SFRP5 are significantly decreased." (PMID 34948320, 2021).
Peritoneal Fibrosis (2 papers, 2020 to 2026). Disorder characterized by a wide range of structural changes in PERITONEUM, resulting from fibrogenic or inflammatory processes. "We co‐expressed TGFB and WNT5A using adenovirus and examined its role in the development of peritoneal fibrosis and angiogenesis." (PMID 32052562, 2020). "Addition of WNT5A to the mouse peritoneum resulted in reduced submesothelial thickness and blood vessel density in TGFB‐induced peritoneal fibrosis." (PMID 32052562, 2020). "In peritoneal fibrosis, the role of Wnt5a is context dependent: its profibrotic or antifibrotic effects depends on ROR2 expression, with ROR2 silencing reversing the antifibrotic and antiangiogenic activity of Wnt5a." (PMID 41541657, 2026).
phyllodes tumor (2 papers, 2005 to 2016). A benign, borderline, or malignant fibroepithelial neoplasm arising from the breast and rarely the prostate gland. "Overexpression of Wnt-5a has been shown to correlate with abnormal nuclear localization of β-catenin protein in phyllodes tumor and ectopic Wnt-11 can rescue axis structures in UV ventralized Xenopus embryos by activation of the Wnt/β-catenin pathway." (PMID 16236168, 2005).
preeclampsia (2 papers, 2020 to 2021). Preeclampsia is a hypertensive disorder of pregnancy that is characterized by new-onset hypertension with proteinuria presenting after 20 weeks of gestation, and depending on mild or severe forms may initially present with severe headache, visual disturbances, and hyperreflexia. "WNT5A signaling play potential roles in human placental and malfunction of it can cause preeclampsia." (PMID 33790866, 2021). "ASP has many physiological effects; we proved ASP prevents kidney damage in LPS-induced preeclampsia by inhibiting the WNT5A and NF-κB signaling pathways in this study." (PMID 33790866, 2021). "So the critical function of WNT5A in preeclampsia related kidney injury is worth studying." (PMID 33790866, 2021).
prostate adenocarcinoma (2 papers, 2024 to 2025). "Our study results revealed lower immunoreactivity and expression of genes encoding β-catenin, Fzd8, Wnt5a, and cyclin D1 and significantly higher fluorescence intensity of miRNA 106a-5p and 375-3p with prostate adenocarcinoma compared to BPH." (PMID 41465498, 2025). "Therefore, the aim of the present study was to perform a pilot evaluation of the expression of miRNAs 106a-5p and 375-3p, as well as β-catenin, Fzd8, Wnt5a, and cyclin D1 in prostate adenocarcinoma compared with BPH." (PMID 41465498, 2025). "Our study results, indicating lower expression of β-catenin, Fzd8, Wnt5a and cyclin D1, may suggest attenuated activity of the Wnt/β-catenin pathway in prostate adenocarcinoma compared to benign prostatic hyperplasia." (PMID 41465498, 2025). "Assessment of immunohistochemical staining intensity through digital image analysis, corroborated by statistical testing, confirmed lower immunoreactivity of β-catenin, Fzd8, Wnt5a and cyclin D1 in prostate adenocarcinoma compared to benign prostatic hyperplasia." (PMID 41465498, 2025). "In our study, we showed reduced expression of Wnt5a in prostate adenocarcinoma, which may indicate a suppressor role of the protein in this tumor." (PMID 41465498, 2025). "In summary, the results of this study showed significantly higher expression of miR-106a-5p and miR-375-3p in prostate adenocarcinoma tissues compared with BPH, accompanied by lower expression of β-catenin, Fzd8, Wnt5a, and cyclin D1." (PMID 41465498, 2025).
psoriasis vulgaris (2 papers, 2016 to 2020). Plaque psoriasis is the most common presentation of psoriasis. "For example, while LCN2, WNT5A, and KRT6 (cluster 1) are all highly up-regulated in psoriasis vulgaris LS, these genes, which show constitutively high expression in scalp NL and N biopsies, are up-regulated to a lesser degree in LS scalp biopsies." (PMID 26849645, 2016).
Pulmonary hypoplasia (2 papers, 2014). "WNT5A negatively regulates SHH expression in the chick lung and overexpression of WNT5A causes pulmonary hypoplasia." (PMID 24743779, 2014). "The overexpression of Wnt5a in transgenic mice and in chicks has been reported to result in severe pulmonary hypoplasia." (PMID 24658098, 2014).
renal carcinoma (2 papers, 2009 to 2021). A carcinoma arising from the epithelium of the renal parenchyma or the renal pelvis. "Regulation of endogenous hTERT by Wnts was not assessed in this study, though Wnt5A was previously shown to suppress telomerase in renal carcinoma cells." (PMID 19649288, 2009).
renal cell carcinoma (2 papers, 2016). "In the renal cell carcinoma TCGA dataset, more than 80% of specimens had lost one or two Wnt5a alleles, which suggested that Wnt5a may play an important role in RCC." (PMID 26942462, 2016).
rheumatic valve disease (2 papers, 2022 to 2025). "In this study, we present baseline plasma concentrations of WNT-5a, sFRP-1, sFRP-5, and WIF-1 in patients with coronary and/or valvular heart disease." (PMID 36440011, 2022).
schizophrenia (2 papers, 2023 to 2024). A major psychotic disorder characterized by abnormalities in the perception or expression of reality. "Univariate and multivariate analyses identified miR-141-3p, Wnt5a, and Arp2 as three possible independent risk factors for schizophrenia." (PMID 36680208, 2023). "Recent studies have demonstrated that aberrant Wnt5a is associated with the pathogenesis of schizophrenia." (PMID 36680208, 2023). "A gene expression study suggests Wnt5a signaling is implicated in the etiology of schizophrenia." (PMID 36680208, 2023). "Reverse transcription-quantitative polymerase chain reaction (RT-qPCR) and enzyme-linked immunosorbent assay (ELISA) showed a significant reduction of Wnt5a and Arp2 in schizophrenia compared with healthy controls." (PMID 36680208, 2023). "ELISA results showed substantially lower Wnt5a expression in schizophrenia compared to healthy controls (9186.80 ± 4941.88 versus 22023.42 ± 12260.12 ng/L, respectively; p < 0.001)." (PMID 36680208, 2023). "We further found decreased mRNA and protein levels of Wnt5a in schizophrenia patients." (PMID 36680208, 2023). "In summary, miR-141-3p, Wnt5a, and Arp2 might be novel potential blood-based biomarkers in schizophrenia." (PMID 36680208, 2023). "Our findings indicated that miR-141-3p, Wnt5a, and Arp2 might be potential clinical blood-based biomarkers or therapeutic targets for schizophrenia." (PMID 36680208, 2023). "Our findings evaluated the plasma levels of Wnt5a in schizophrenia patients." (PMID 36680208, 2023). "We found that ERVWE1 downregulated Wnt5a and Wnt5a could reversed the neuron damage caused by the ERVWE1 and miR-141-3p, denoting that Wnt5a might improve motor and cognitive impairment during the pathogenesis of schizophrenia." (PMID 36680208, 2023). "In our literature survey, we found three genes in the isoform layer of models have schizophrenia-related reports (cytochrome P450 2D6 (CYP2D6), WNT5A, CD46)." (PMID 37738675, 2024). "Our study showed that ERVWE1 inhibited the activity of RAC1 and WAVE1 through Wnt5a in neurons, suggesting that ERVWE1 triggered schizophrenia by regulating RAC1 and WAVE1 in schizophrenia." (PMID 36680208, 2023). "We interestingly find that ERVWE1 inhibited the Wnt5a signal transduction through Wnt/JNK non-canonical pathway, implying that ERVWE1 might cause abnormal nerve cell function by inhibiting the Wnt signaling pathway, eventually leading to schizophrenia." (PMID 36680208, 2023). "Our clinical data revealed a negative correlation between Wnt5a and ERVWE1 in schizophrenia patients." (PMID 36680208, 2023). "Moreover, serum Wnt5a and actin-related protein 2 (Arp2) levels decreased and demonstrated a significant negative correlation with ERVWE1 in schizophrenia." (PMID 36680208, 2023).
silicosis (2 papers, 2020 to 2024). Silicosis is a respiratory disease caused by breathing in (inhaling) silica dust. "Si activates Wnt5a/Ca+2 signaling and endoplasmic reticulum stress, leading to mitochondrial redox imbalance and ferroptosis in mouse macrophages, a process that underlies silicosis." (PMID 38792655, 2024).